CDKN2A (cyclin dependent kinase inhibitor 2A)
Diseases named in the same sentence as CDKN2A in open-access papers (continued):
Sharing a sentence is not in itself a finding about the gene and the disease.
colon carcinoma (continued). "Among the downregulated genes, we selected CDKN2A and CXCL8 as targets to further explore their roles in colon cancer progression." (PMID 39188951, 2024). "In particular, SFN-treated tissue lysates from colon tumors displayed decreased HDAC3 levels and CDKN2a/p16 mRNA expression and enhanced global histone H4 acetylation." (PMID 36765652, 2023). "The GSE10950 dataset showed that CDKN2A and CMTM8 mRNA expression levels were up-regulated in colon cancer samples, while ILK was considerably down-regulated in colon cancer samples." (PMID 35429970, 2022). "We performed experiments in detecting protein expression of CDKN2A, CMTM8 and ILK by immunohistochemistry in the colon cancer tissues and adjacent tissues." (PMID 35429970, 2022). "To sum up, we found that CDKN2A and CMTM8 were up-regulated in colon cancer, while, ILK was down-regulated." (PMID 35429970, 2022). "It has been reported that TSA can activate certain hypermethylated genes, including CDKN2B, CDKN2A, MLH1 and TIMP3 in colon cancer cells after Dnmt1 inhibition by DNA demethylating agent such as 5-aza-dc." (PMID 32334468, 2020). "Structural variations were relatively infrequently to find three cases of CDKN2A, ERBB2 and EGFR amplification and single one RET-NCOA fusion in a young patient with sporadic, left colon cancer (MSI-S)." (PMID 26909603, 2016). "In total, 31 CpG sites, located in 8 different genes (RUNX3, MLH1, NEUROG1, CDKN2A, IGF2, CRABP1, SOCS1 and CACNA1G) were investigated in 64 distinct colon cancers and 2 colon cancer cell lines." (PMID 24466191, 2014). "Studies of lung and colon cancer show that underexpression of DLC1 frequently co-occurs with deregulated expression of cell cycle genes such as CDK6, CDK4, CDKN2A, and CDKN2B." (PMID 25425654, 2014). "A study reported that CDKN2A hyper-methylation was found in 100% of colon cancer cell lines and 55% of colon cancers, but not in colonic epithelium." (PMID 39125664, 2024). "Based on these observations, we hypothesized that CXCL8 and CDKN2A are key regulators of cell senescence in HT29 and HCT116 colon cancer cells by shikonin." (PMID 39188951, 2024). "CDKN2A and CXCL8 were highly expressed in colon cancer and various other tumors." (PMID 39188951, 2024). "So, CDKN2A, CMTM8 and ILK may affect the prognosis of colon cancer by influencing EMT and immune simultaneously." (PMID 35429970, 2022). "CDKN2A, CMTM8 and ILK are promising prognostic biomarkers and may be potential therapeutic targets in colon cancer." (PMID 35429970, 2022). "Combined with our results, it can be inferred that the up-regulated CDKN2A, CMTM8, and down-regulated ILK may aggravate the progression of EMT by the TGF-β pathway in colon cancer, as a result, promoting the infiltration and metastasis." (PMID 35429970, 2022). "To verify whether shikonin should potentially induce cell senescence in colon cancer cells by downregulating the expression of CDKN2A and CXCL8, we used a SA-β-Gal staining experiment to detect the senescent cells in the colon cancer cells that were treated with shikonin." (PMID 39188951, 2024). "In colon cancer, most likely because of the lack of data, cross-correlation identified only three correlating groups (EIF4E3/MEX3A, SSR1/RPL39L, and PPARGC1B/CDKN2A)." (PMID 39940786, 2025).
gastric cancer (88 papers, 2002 to 2026). A primary or metastatic malignant neoplasm involving the stomach. "Immunohistochemical MTAP loss consistently co-occurred with homozygous CDKN2A deletion and was present in 25.5% of cholangiocarcinomas, 9.3% of esophageal adenocarcinomas, 10.3% of gastric carcinomas, and 30.2% of pancreatic adenocarcinomas." (PMID 42129334, 2026). "Our analysis highlights the high mutation rate of CDKN2A among cuproptosis-related genes, corroborating its established role as a tumor suppressor frequently altered in various cancers, including gastric cancer." (PMID 40410601, 2025). "Previous studies in gastric cancer have reported that CDKN2A loss confers a cold tumor immune microenvironment." (PMID 38822443, 2024). "the aim of this study was to assess the association between the CDKN2A / B rs10811661 polymorphism, tumor grade and tumor invasiveness in individuals with colon and gastric cancer." (PMID 37845622, 2023). "In conclusion, our results advocate that there is a link between a CDKN2A / B gene polymorphism (rs10811661) and a poor prognosis in sufferers of colorectal and gastric cancer." (PMID 37845622, 2023). "CDKN2A is frequently mutated in gastric cancer, resulting in cell invasion, migration, and colony formation." (PMID 35242169, 2022). "Promoter methylation in a subset of gastric cancer patients is associated with the CpG island methylator phenotype, which includes methylation of such genes as CDKN2A and hMLH1." (PMID 28418867, 2017). "We analyzed the scRNA-seq profiles of 21 primary gastric cancers (n = 59,594 cells), 20 of which were CDKN2A WT and one were CDKN2A-mutant (Missense Mutation) based on WES, to determine if CDKN2A ALT in gastric cancer was significantly associated with decreased inflammation." (PMID 38822443, 2024). "ARID1A is a frequently mutated gene in gastric cancers (GCs), particularly in those associated with the Epstein-Barr virus (EBV), which also often shows PIK3CA mutations and CDKN2A silencing." (PMID 40761291, 2025). "Copper death related genes such as LIAS, GLS, and CDKN2A can regulate the function of immune cells, affect the occurrence and development of gastric cancer, and serve as biomarkers for gastric cancer patients." (PMID 41158129, 2025). "Among gastric cancer sub-types, MSI-high and EBV-associated cancers displayed the frequent methylation of CDKN2A, encoding for p16, and were abemaciclib-sensitive." (PMID 40699853, 2025). "The examination of the gastric cancer scRNA-seq data revealed that the tumors from CDKN2A-ALT patients had more exhausted CD8 T cells than those from CDKN2A WT patients." (PMID 38822443, 2024). "Gastric cancer scRNA-seq data also showed that CDKN2A-ALT cancer contained less CD8 T cells but more exhausted T cells than CDKN2A-WT cancer." (PMID 38822443, 2024). "In contrast, the most frequent deletion in gastric cancers at chromosome 9p21.3, encompassing the locus of tumor suppressor CDKN2A, had similar prevalence in the two groups (Fisher’s exact test p = 0.52)." (PMID 39768557, 2024). "A crucial finding of the pathway analysis was the inhibition of three immune-related pathways in the CDKN2A ALT gastric cancer patients, including the interferon alpha response, inflammatory response, and interferon gamma response." (PMID 38822443, 2024). "We used the TCGA gastric cancer dataset to compare the expression levels of the p14 ARF (p14) and p16INK4a (p16) proteins in the CDKN2A mutant group and found that the p16 protein was considerably less expressed than the p14 protein." (PMID 38822443, 2024). "They found 5.1 kb CDKN2A common deletion regions (CDR) in >90% of gastric cancers containing CDKN2A deletion." (PMID 39457569, 2024). "This study aims to determine the associations of CDKN2A MUT and DEL with overall survival (OS) and response to immune checkpoint inhibitors treatment (ICIs) among pan-cancers and the clinical features of CDKN2A-altered gastric cancer." (PMID 38822443, 2024).
gastric cancer (continued). "Approximately 30% of gastric carcinomas exhibit CDKN2A methylation, potentially contributing to the malignant transformation of gastric lesions." (PMID 38542354, 2024). "We are aware that CDKN2A and MLH1 silencing are common epigenetic events in gastric carcinomas and are associated with cell-cycle regulation and DNA repair mechanisms." (PMID 38542354, 2024). "In gastric carcinomas, EBV status, CIMP phenotype, as well as MLH1 and CDKN2A methylation status, were strongly associated with methylated PD-L2." (PMID 38542354, 2024). "Association of somatic copy number variations (SCNVs) of the CDKN2A gene by P16-Light with clinicopathological characteristics of Chinese patients with gastric carcinoma (GC) included in a cross-sectional study and a prospective study." (PMID 35004325, 2021). "In gastric cancer, a large number of genes (e.g., CDKN2A, CDK2AP2, CDH1, MGMT, RASSF1, RUNX3, and DLC1) have been shown to be suppressed by CpG island hypermethylation." (PMID 23179365, 2013). "The predicted RB-negative frequencies determined by the cut-off value of log10 (CCND1/CDKN2A) of 0.404 were 100% (7/7), 22% (2/9), 100% (5/5), and 5% (1/20) in cervical, endometrial, small cell lung, and gastric cancers, respectively." (PMID 21447152, 2011). "We found that uterine cervical and small cell lung cancers were predicted to be RB-negative at high prevalence, while most uterine endometrial and stomach cancers were predicted to be RB1-positive by the CCND1/CDKN2A assay." (PMID 21447152, 2011). "We and others have shown that naturally infected gastric cancers have lower CDKN2A (p16) expression." (PMID 21194482, 2010). "In a clinical trial of fluorouracil (5FU) for gastric cancer, CDKN2A promoter methylation status was an independent predictor of survival." (PMID 21194482, 2010). "Candidate mutations include recurrent gastric cancer driver alterations, while promoter methylation of genes such as CDH1, CDKN2A (p16), and RUNX3 may serve as epigenetic readouts of field cancerization." (PMID 41479890, 2025). "Other frequently deleted genes in gastric cancer, PRKN (encoding for ubiquitin ligase Parkin, also located at a fragile site), and for CDK inhibitor CDKN2A, were also more frequently observed in the up-regulated group, without reaching significance (Student’s t-test p = 0.13 and 0.21, respectively)." (PMID 41425714, 2025). "For instance, the H. pylori cytotoxin-associated gene A (CagA) protein not only promotes hypermethylation of tumor-suppressor genes like CDKN2A but also interacts with E-cadherin, disrupting β-catenin signaling in epithelial cells, thereby contributing to gastric cancer tumorigenesis." (PMID 40264971, 2025). "Interestingly, our findings also revealed that CDKN2A-ALT patients displayed a cold tumor immune microenvironment in gastric cancer single-cell data analysis." (PMID 38822443, 2024). "Fourth, only single-cell data from CDKN2A point mutation study of stomach cancer were given, not those from single-cell analysis of CDKNA DEL patients." (PMID 38822443, 2024). "However, CDKN2A is highly expressed in gastric precancerous lesions but decreased expression in gastric cancer stage." (PMID 36600891, 2022). "CDKN2A promoter methylation has been reported in 30% of gastric cancer cases." (PMID 25997695, 2015). "Our findings demonstrated that CDKN2A VAR promoted cell proliferation by reducing expression of p16 with function as a regulator of the cell cycle of inhibiting CDK4 and CDK6 in gastric cancer." (PMID 38822443, 2024).
gastric cancer (continued). "The purpose of the conducted research was to evaluate the mechanism and involvement of methylation in regards to the CDKN2A gene and the specific locus region in gastric cancer (GC) with comprehensive statistical analysis utilizing statistics acquired from The Cancer Genome Atlas (TCGA) database." (PMID 33896386, 2021). "Methylation of genes such as RARB2, APC, CDKN2A, and RUNX3 has been shown to decrease following surgery in breast, esophageal, liver, and gastric cancers." (PMID 31615043, 2019). "CDKN2A was also a DNA methylation-sensitive gene, being consistent with previous reports that CDKN2A is hypermethylated and silenced in EBV-positive gastric cancer." (PMID 28903418, 2017). "CDDP-resistant gastric cancer cells exhibit ABCB1 and CDKN2A gene up-regulation, as compared with CDDP-sensitive gastric cancer cells." (PMID 23672493, 2013). "An anti-correlation of RB1 and CDKN2A expression was also reported in SCLC, gastric cancer, oral cavity squamous carcinoma or urinary bladder cancer." (PMID 21447152, 2011). "Next, western blotting revealed a downregulation of p16 but no change in p14 expression in CDKN2A knockdown gastric cancer cell lines (AGS and HGC-27)." (PMID 38822443, 2024). "Some of these markers have been identified for their potential functions in cancer: FDX1 can be activated by SF1 and cJUN in Leydig cells, CDKN2a usually functions as a tumor suppressor in many cancers, and DLAT has also been reported to be an oncogene in gastric cancer." (PMID 37190215, 2023). "Hypermethylated CDKN2A (p16INK4a) and DCTPP1 might be useful biomarkers for 5-FU-sensitive gastric cancer." (PMID 35309131, 2022). "Further, in gastric cancer, as EBV-induced hypermethylation targets and silences key tumor suppressor genes including APC, RASSF1, BRCA1, THBS1, and CDKN2A, DNA methyltransferase inhibitors may also serve as a new therapeutic treatment for patients with EBV-positive gastric cancer." (PMID 37234978, 2023). "EBV-positive gastric carcinomas are characterized by the monoclonal proliferation of EBV-infected cancer cells, global CpG island methylation of cancer-related genes, unique methylation patterns leading to CDKN2A (p16) downregulation, and hyperactive T-cell activation." (PMID 27438138, 2016). "RASSF1A, p14ARF, and MGMT; CHRNA3, DOK1, and GNMT; p16, hMLH1, MINT1, MINT2, MINT12, MINT25, and MINT31; APC, CDH1, MHL1, CDKN2A, CDKN2B, and RUNX3; CDH1; DKK3; PTEN; MGMT; TFPI2; CACNA2D3; PCDH10; SOX2; MAL; and COX2 were previously reported to be hypermethylated in gastric cancer." (PMID 26121593, 2015). "However, some genes (CHEK1, CDKN1A, CDKN2A, CCNB1, etc.)from the B-terms of the close discovery were cell cycle regulators, suggesting that anandamide might be related to cell cycle in gastric cancer." (PMID 24949851, 2014). "Furthermore, an examination of single-cell data in gastric cancer has demonstrated that tumors originating from patients with CDKN2A-ALT exhibit a higher abundance of fatigued CD8 T cells and a lower abundance of regulatory T cells compared to tumors from CDKN2A WT individuals." (PMID 38822443, 2024). "Lastly, a CCND1/CDKN2A assay with clinical samples showed that uterine cervical and small cell lung cancers known to have a high prevalence of RB1-decifiency were predicted to be 100% RB1-negative, while uterine endometrial or gastric cancers were predicted to be 5-22% negative." (PMID 21447152, 2011).
osteosarcoma (87 papers, 2004 to 2026). A usually aggressive malignant bone-forming mesenchymal neoplasm, predominantly affecting adolescents and young adults. "Here, we present a case of a woman with LFS and therapy-refractory osteosarcoma with homozygous loss of cyclin dependent kinase inhibitor 2 A (CDKN2A) in the tumor cells." (PMID 39820556, 2025). "Subsequent molecular analysis of the osteosarcoma tissue revealed homozygous loss of the CDKN2A gene locus, warranting treatment with CDK4/6 inhibitor palbociclib." (PMID 39820556, 2025). "Somatic mutation of CDKN2A has a known association with bone sarcomas, and in particular osteosarcoma; nevertheless, accumulating evidence has suggested that germline variants are linked with osteosarcoma as well." (PMID 38730621, 2024). "We found the germline CDKN2A c.350del (p.Leu117ArgfsTer29) pathogenic variant in a patient with osteosarcoma." (PMID 36805510, 2023). "This second GWAS emphasizes the association of the CDKN2A/CDKN2B locus with osteosarcoma development in large and giant dog breeds." (PMID 37505880, 2023). "The patient with a CDKN2A germline pathogenic variant developed a fatal metastatic relapse during the osteosarcoma therapy." (PMID 36805510, 2023). "Loss of p16INK4A protein expression as a result of homozygous loss of the CDKN2A genomic region has previously been shown to correlate with poor prognosis as well as a poor response to neoadjuvant chemotherapy in osteosarcoma patients." (PMID 34921235, 2022). "Homozygous deletion of the CDKN2A locus, which is associated with poor prognosis in osteosarcoma, eradicates both expression of p16Ink4A and p14ARF, of which the latter is a negative regulator of MDM2." (PMID 31741049, 2020). "The landmark study of Karlsson, Lindblad-Toh and associates included three osteosarcoma GWAS’s in different breeds with high risk – Greyhound, Rottweiler and Irish Wolfhound – as well as supporting evidence for a CDKN2A/B/ANRIL haplotype in other breeds." (PMID 30890123, 2019). "In both osteosarcoma (p = 1.4 × 10−3) and lung cancer models (p = 3.5 × 10−2), we identified an association between mutation/deletion of CDKN2A and dependency upon the cyclin dependent kinase gene CDK11A, which encodes a CDKN2A interacting protein." (PMID 26947069, 2016). "Amplification of CDK4 and loss of RB1, or CDKN2A loss are considered nearly universal in osteosarcoma with 20% of cases having either amplification of CDK4 or deletion of CDKN2A." (PMID 27074562, 2016). "The greyhound locus exhibiting the strongest association, located 150 kilobases upstream of the genes CDKN2A/B, is also the most rearranged locus in canine osteosarcoma tumors." (PMID 24330828, 2013). "It would be interesting to consider CDKN2A germline alterations in patients with osteosarcoma that may be associated with a cancer predisposition syndrome, especially in those cases where LFS is ruled out." (PMID 36805510, 2023). "Thus, our results combined with previously published results, suggest that loss of CDKN2A/CDKN2B is an early driver event in osteosarcoma." (PMID 34921235, 2022). "Interestingly, the strongest association, located upstream of the CDKN2A/B genes on canine chromosome 11, is also the most rearranged locus in canine osteosarcoma tumors." (PMID 34946912, 2021). "Somatic mutation of CDKN2A in canine osteosarcoma also includes frequent sequence changes." (PMID 30890123, 2019). "However, there is additional evidence specifically implicating CDKN2A in osteosarcoma: somatic mutation in dogs and germ line mutagenesis in mice." (PMID 30890123, 2019).